ZNF267 (zinc finger protein 267)
Description:
May be involved in transcriptional regulation.
Synonyms: HZF2
Tractability: PROTAC: UniProt records ubiquitination sites on it; ubiquitination databases record sites on it.
Gene: Protein-coding gene on chromosome 16 (31,873,788 to 31,917,357, forward strand). Ensembl gene ENSG00000185947.
Subcellular location: Nucleus
Subcellular location (Human Protein Atlas): Nucleoplasm
Pathways (Reactome):
Gene expression (Transcription): Generic Transcription Pathway
Gene Ontology:
Molecular function: transcription cis-regulatory region binding
Biological process: negative regulation of transcription by RNA polymerase II; regulation of DNA-templated transcription
Cellular component: nucleus; cytoplasm
Genetic constraint (gnomAD): Loss-of-function variants: 61 observed, 75.08 expected, observed/expected ratio (o/e) 0.81, 90% interval 0.66 to 1.01. The upper end of that interval is the gene's LOEUF score, 1.01, which puts it in group 4 of 6, group 1 being the genes least tolerant of losing a copy. Missense variants: 852 observed, 911.19 expected, observed/expected ratio (o/e) 0.94, 90% interval 0.88 to 0.99. Synonymous variants: 288 observed, 305.95 expected, observed/expected ratio (o/e) 0.94, 90% interval 0.85 to 1.04.
Homologues: Orthologues: chimpanzee ZNF267 (99% identical), macaque ZNF267 (96% identical). Paralogues in human: ZNF841 (44% identical), ZNF546 (43% identical), ZNF836 (43% identical), ZNF540 (40% identical), ZNF30 (40% identical), ZNF254 (39% identical), ZNF616 (39% identical), ZNF726 (38% identical), ZNF724 (38% identical), ZNF528 (38% identical), ZNF571 (37% identical), ZNF85 (37% identical), and 164 more.
Diseases named in the same sentence as ZNF267 in open-access papers:
ZNF267 is named in the same sentence as 18 diseases in open-access papers, as found by Europe PMC text mining. Sharing a sentence is not in itself a finding about the gene and the disease. The quoted sentences say what the papers report.
hepatocellular carcinoma (2 papers, 2023 to 2025). A malignant tumor that arises from hepatocytes. "Previous studies have demonstrated that ZNF267 is upregulated in hepatocellular carcinoma (HCC) and contributes to tumor progression by promoting cell proliferation and migration." (PMID 40075430, 2025).
osteoporosis (2 papers, 2023 to 2025). A condition of reduced bone mass, with decreased cortical thickness and a decrease in the number and size of the trabeculae of cancellous bone (but normal chemical composition), resulting in increased fracture incidence. "Certain proteins, including zinc finger protein 267 (ZNF267), ras homologue family member J, actin-binding LIM protein family member 2, programmed cell death 1, and cell cycle protein-dependent kinase-like 5, have been implicated in the pathogenesis of osteoporosis." (PMID 40041284, 2025).
autism spectrum disorder (1 paper, 2025). A spectrum of developmental disorders that includes autism, and Asperger syndrome. "Unlike this trend, some KRAB-ZNFs linked to cognitive disorders were human specifically upregulated, e.g., ZNF778, a candidate gene for autism spectrum disorder and cognitive impairment, and ZNF267, which is upregulated in the prefrontal cortex of AD patients." (PMID 40928843, 2025).
dementia (1 paper, 2021). Loss of intellectual abilities interfering with an individual's social and occupational functions. "Other differentially expressed genes have been previously associated with dementia (ITM2B, MAPT, ZNF267, and DHX37)." (PMID 34194426, 2021).
non-alcoholic fatty liver disease (1 paper, 2025). "In the study on ZNF267 and non-alcoholic fatty liver disease (NAFLD), it has been pointed out that hepatocellular lipid accumulation induced formation of reactive oxygen species (ROS), and also increased ZNF267 mRNA expression." (PMID 40075430, 2025).
ovarian carcinoma (1 paper, 2011). A malignant neoplasm originating from the surface ovarian epithelium. "In HIO-80 cells, there was significant upregulation of genes encoding for proteins associated with ovarian cancer metastasis [SERPINB2/PAI2], metabolic activities [IDI1, PMM2] and gene expression/transcription [PCGF6, ZNF267]." (PMID 22022533, 2011). "The upregulated genes encode for proteins associated with ovarian cancer metastasis [SERPINB2/PAI2], metabolic activities [IDI1, PMM2] and gene expression/transcription [PCGF6, ZNF267]." (PMID 22022533, 2011).
polycystic kidney (1 paper, 2025). "In summary, we hypothesize that loss of function of ETFDH gene may lead to polycystic kidney by upregulating ZNF267 expression." (PMID 40075430, 2025). "The functional role of ETFDH and ZNF267 in polycystic kidney diseases remains unknown, which opens up new avenues for research into the pathogenesis of polycystic kidney disease and tumors." (PMID 40075430, 2025).
postmenopausal osteoporosis (1 paper, 2020). Metabolic disorder associated with fractures of the femoral neck, vertebrae, and distal forearm. "Clinical evidence shows that the methylation state of CpG sites of zinc finger protein 267 (ZNF267), actin binding LIM protein family member 2 (ABLIM2), Ras homolog family member J (RHOJ), and cyclin dependent kinase like 5 (CDKL5) genes is correlated with postmenopausal osteoporosis." (PMID 32664681, 2020).
tumor (3 papers, 2023 to 2025). "ZNF267 has been reported involved in tumor cell proliferation and migration in the previous study." (PMID 39896809, 2024). "Although studies have suggested that ZNF267 is involved in tumor progression, its role in CRC metastasis is largely unknown." (PMID 36691044, 2023). "Although the role of LARP6 and ZNF267 in CRC differs from that in other tumors, it is frequent in tumor studies that gene distinctively regulates cancer development in different tumor types or even shows opposing effects." (PMID 36691044, 2023).
benign neoplasm (1 paper, 2024). A neoplasm which is characterized by the absence of morphologic features associated with malignancy (severe cytologic atypia, tumor cell necrosis, and high mitotic rate). "There have been documented EGFR::ZNF267 gene fusions and increased mutation rates in heteroplasmy in SH, suggesting it as a benign neoplasm." (PMID 39281855, 2024).
infection (1 paper, 2023). The state of being infected such as from the introduction of a foreign agent such as serum, vaccine, antigenic substance or organism. "Briefly explaining, figuratively, the initiation of infection with SARS-CoV-2 using ACE2 as a receptor for viral entry and infectivity is augmented by ZFPs like ZDHHC18, ZNF267, and ZC3H11A (seen in Omicron infection)." (PMID 38025778, 2023).
ZNF267 also shares sentences with these, for which no sentence is quoted: cancer (2 papers); acute lymphoblastic leukaemia (1); cervical cancer (1); cognitive disorder (1); colorectal cancer (1); diffuse large B-cell lymphoma (1); endometriosis (1).